LPAR6 (lysophosphatidic acid receptor 6)
Description:
Binds to oleoyl-L-alpha-lysophosphatidic acid (LPA). Intracellular cAMP is involved in the receptor activation. Important for the maintenance of hair growth and texture.
Synonyms: LPA-6; P2Y5; P2RY5; ARWH1; HYPT8; LAH3
Tractability: Small molecule: a structure with a bound ligand is known; a high-quality ligand is known; it belongs to a druggable protein family. Antibody: UniProt places it where antibodies can reach, with high confidence; its Gene Ontology location is reachable by antibodies, with high confidence; UniProt predicts a signal peptide or a membrane-spanning region; the Human Protein Atlas places it where antibodies can reach. PROTAC: a small molecule that binds it is known.
Target class: EDG receptor; Family A G protein-coupled receptor; Lipid-like ligand receptor (family A GPCR); Membrane receptor; Small molecule receptor (family A GPCR)
Gene: Protein-coding gene on chromosome 13 (48,389,567 to 48,444,704, reverse strand). Ensembl gene ENSG00000139679.
Subcellular location: Cell membrane
Subcellular location (Human Protein Atlas): Plasma membrane; Vesicles
Pathways (Reactome):
Signal Transduction: G alpha (q) signalling events; P2Y receptors
Gene Ontology:
Molecular function: protein binding; lysophosphatidic acid receptor activity; G protein-coupled receptor activity
Biological process: G protein-coupled receptor signaling pathway
Cellular component: plasma membrane; membrane
Genetic constraint (gnomAD): Loss-of-function variants: 17 observed, 22.82 expected, observed/expected ratio (o/e) 0.74, 90% interval 0.51 to 1.12. The upper end of that interval is the gene's LOEUF score, 1.12, which puts it in group 4 of 6, group 1 being the genes least tolerant of losing a copy. Missense variants: 378 observed, 418.37 expected, observed/expected ratio (o/e) 0.9, 90% interval 0.83 to 0.98. Synonymous variants: 135 observed, 143.96 expected, observed/expected ratio (o/e) 0.94, 90% interval 0.81 to 1.08.
Homologues: Orthologues: chimpanzee LPAR6 (100% identical), rabbit LPAR6 (94% identical), mouse Lpar6 (93% identical), rat Lpar6 (93% identical), guinea pig LPAR6 (91% identical), dog LPAR6 (90% identical), pig LPAR6 (85% identical), tropical clawed frog lpar6 (79% identical), zebrafish lpar6a (62% identical), zebrafish lpar6b (56% identical). Paralogues in human: LPAR4 (52% identical), CYSLTR1 (29% identical), GPR17 (28% identical), CYSLTR2 (28% identical), F2R (28% identical), P2RY10 (26% identical), GPR55 (26% identical), GPR4 (25% identical), GPR65 (25% identical), F2RL2 (25% identical), GPR35 (25% identical), P2RY8 (25% identical), and 4 more.
Diseases named in the same sentence as LPAR6 in open-access papers:
LPAR6 is named in the same sentence as 63 diseases in open-access papers, as found by Europe PMC text mining. Sharing a sentence is not in itself a finding about the gene and the disease. The quoted sentences say what the papers report.
hepatocellular carcinoma (12 papers, 2016 to 2025). A malignant tumor that arises from hepatocytes. "LPAR6 (lysophosphatidic acid receptor 6) is the G protein-coupled receptor of the LPA family, and it has been known to be associated with cancer types such as hepatocellular carcinoma, pancreatic cancer and prostate cancer." (PMID 40870024, 2025). "In summary, by combining transcriptomics, we explored the function and mechanisms of LPAR6 at the cell, tissue, and animal levels, and found that LPAR6 acts as a tumor-suppressive receptor in hepatocellular carcinoma." (PMID 40362442, 2025). "Although previous studies have suggested that LPAR6 served as an oncogene in hepatocellular carcinoma and pancreatic carcinoma, it is rational to consider, from our results, that in breast cancer, LPAR6 acts as an antitumor factor." (PMID 34510318, 2022). "LPAR6 expression in hepatocellular carcinoma correlated with poorer survival and increased microvascular invasion." (PMID 34209775, 2021). "The 4-methylene-2-octyl-5-oxotetra-hydrofuran-3-carboxylic acid (C75) and xanthenylacetic acid (XAA) for LPAR6 ameliorated hepatocellular carcinoma growth through modulating mitochondria homeostasis and arresting cancer cells at the G1-phase cell cycle." (PMID 34209775, 2021). "LPAR6 is involved in maintaining proliferation capacity and tumorigenic phenotype in the hepatocellular carcinoma." (PMID 29211777, 2017). "Similarly, LPAR6 expression in hepatocellular carcinoma patients correlates with a better prognosis and higher tumour immune cell infiltration." (PMID 38607068, 2024). "Similarly, depletion of Lysine-specific demethylase 1 (LSD1) and elevated expression of matrix metallopeptidase-9 (MMP-9) leads to an enhanced expression of LPAR6 in hepatocellular carcinoma." (PMID 29211777, 2017). "Moreover, LPAR6 promotes hepatocellular carcinoma proliferation via the NCOA3-LPAR6-HGF signaling cascade, and the tumor-suppressive effect by depletion of LPAR6 is similar to that of anti-HGF treatment." (PMID 34209775, 2021).
breast carcinoma (9 papers, 2021 to 2025). "To realize other potential mechanisms underlying the effects of LPAR6 on breast cancer, we performed GSEA using TCGA and METABRIC datasets." (PMID 34510318, 2022). "In vitro gain and loss-of-function assays indicated that LPAR6 attenuated breast cancer cell proliferation." (PMID 34510318, 2022). "Higher level of LPAR6 is associated with a better prognosis in three types of cancers, including liver cancer, lung cancer and breast cancer." (PMID 34769557, 2021). "In the present study, we did not observe a significant increase or decrease in mRNA expression of LPAR1, LPAR3, and LPAR6 RNA in breast cancer cells after irradiation." (PMID 39338222, 2024). "LPAR6 appears to be positively regulated by miR-27a-3p, as knocking down this miRNA induces LPAR6 overexpression to attenuate breast cancer cell proliferation." (PMID 38607068, 2024). "In this study, the functions and regulatory mechanisms of LPAR6 in breast cancer were investigated further." (PMID 34510318, 2022). "To determine the biological functions of LPAR6 in breast cancer, we performed knockdown and overexpression assays of LPAR6." (PMID 34510318, 2022). "We demonstrated that LPAR6 acts as a tumor suppressor in breast cancer and that miR-27a-3p positively regulated LPAR6 expression and, hence, attenuated cell proliferation in breast cancer." (PMID 34510318, 2022). "Taken together, the results demonstrate that miR-27a-3p positively regulates LPAR6 mRNA levels and attenuates cancer cell proliferation via LPAR6 in breast cancer." (PMID 34510318, 2022). "In our study, we found that miR-27a-3p positively regulated LPAR6 expression and attenuated cell proliferation in luminal-type breast cancer cell line." (PMID 34510318, 2022). "Although further researches need to be conducted, the miR-27a-3p-LPAR6 axis is a promising therapeutic target in breast cancer." (PMID 34510318, 2022). "Western blotting was performed to validate the differential expression of LPAR6 in breast cancer tissues and their adjacent tissues." (PMID 34510318, 2022). "Multiple public databases were used to investigate the mRNA expression of LPAR6, its prognostic value, and potential mechanisms in breast cancer." (PMID 34510318, 2022). "Overall, LPAR6 expression is downregulated in breast cancer, and this is correlated with poor clinicopathological features, including pathological grades and clinical stages, which indicates that LPAR6 acts as a suppressor in breast cancer." (PMID 34510318, 2022). "Decreased LPAR6 expression in breast cancer is significantly correlated with poor overall survival, disease-free survival, and distal metastasis-free survival, particularly for hormone receptor-positive patients, regardless of lymph node metastatic status." (PMID 34510318, 2022). "In breast cancer, the expression level of LPAR6 is significantly downregulated, and miR-27a-3p can positively regulate the expression of LPAR6 and affect the function of cell cycle signalling pathway." (PMID 35978806, 2022). "The bc-GenExMiner v4.6 was used to analyze the prognostic value of LPAR6 expression in breast cancer." (PMID 34510318, 2022). "The present study provides further evidence for the expression, prognostic value, and potential mechanism of LPAR6 in breast cancer." (PMID 34510318, 2022). "It is also demonstrated that miR-27a-3p positively regulates LPAR6 expression, thereby attenuating cell proliferation in breast cancer." (PMID 34510318, 2022). "To investigate LPAR6 effects on the inhibition of breast cancer progression, we investigated its significantly correlated or co-expressed genes via in silico analysis." (PMID 34510318, 2022). "Taken together, LPAR6 inhibits breast cancer growth via attenuating cell proliferation and acts as a tumor suppressor in breast cancer." (PMID 34510318, 2022). "The regulation of the miR-27a-3p/LPAR6 axis would be a potential therapeutic strategy for breast cancer." (PMID 34510318, 2022).
breast carcinoma (continued). "By exploring the METABRIC dataset, LPAR6 was significantly downregulated in breast cancer tissues compared with that in normal controls." (PMID 34510318, 2022). "First, although we demonstrated the functions and potential upstream regulatory mechanism of LPAR6 in breast cancer, the downstream pathways should be investigated further." (PMID 34510318, 2022). "The expression of LPAR6 was suppressed in breast cancer tissue, and low expression was correlated with poor prognosis." (PMID 34440828, 2021). "In contrast, in breast cancer, LPAR6 acts as a tumor suppressor." (PMID 40362442, 2025). "Low expression of LPAR6 in breast cancer tissue was correlated with poor prognosis." (PMID 39338222, 2024). "LPAR6, on the other hand, is considered to have a protective effect and might act as a tumor suppressor in breast cancer." (PMID 39338222, 2024). "In contrast, LPAR6 may act as an antitumor factor and inhibit cancer cell motility in colon cancer, and this antitumor role may exist in breast cancer." (PMID 34510318, 2022). "To validate the clinical effects of LPAR6 in breast cancer, we analyzed its prognostic value." (PMID 34510318, 2022). "To date, research on LPAR6 in breast cancer is relatively rare." (PMID 34510318, 2022). "Interestingly, bioinformatics analyses of the two large datasets revealed that hallmark E2F, G2/M checkpoint, and myc target pathways were all significantly suppressed with regard to LPAR6 in breast cancer." (PMID 34510318, 2022). "LPAR6 was significantly downregulated in breast cancer at transcriptional and translational levels." (PMID 34510318, 2022). "However, the biological functions and regulatory mechanisms of LPAR6, particularly its relationship with microRNA, in breast cancer are unclear and need further research." (PMID 34510318, 2022). "Notably, LPAR6 was downregulated in breast cancer tissues among all ethnicities, particularly in African American and Asian groups, compared with Caucasians." (PMID 34510318, 2022). "The results showed that decreased LPAR6 expression in all patients with breast cancer was significantly correlated with poorer OS, disease-free survival (DFS), and distal metastasis-free survival (DMFS) compared with that in patients with high LPAR6 expression." (PMID 34510318, 2022). "LPAR6 acts as a tumor suppressor in breast cancer and is positively regulated by miR-27a-3p." (PMID 34510318, 2022). "Therefore, the miR-27a-3p/LPAR6 axis would be a potential target for the therapeutic strategy of breast cancer." (PMID 34510318, 2022). "Additionally, the results from GBA method predict other possible functions of LPAR6 in breast cancer, indicating several convincible directions for future research." (PMID 34510318, 2022). "Bioinformatics analyses reveal that LPAR6 acts as a tumor suppressor in breast cancer and may inhibit tumor progression by facilitating the formation of RB1/E2F family complexes to induce cell cycle arrest." (PMID 34510318, 2022). "Moreover, three cohorts (GSE19615, GSE9195 and GSE11121) of breast cancer demonstrated that higher expression level of LPAR6 was correlated with a better prognostic potential of DMFS." (PMID 34769557, 2021). "In an opposing example, Tao and co-workers explored the role of LPAR6 in breast cancer." (PMID 34440828, 2021). "Furthermore, in vitro experiments were used to explore the effects of LPAR6 on breast cancer." (PMID 34510318, 2022). "Therefore, we inferred that LPAR6 may inhibit breast cancer growth via activating Gαs-AC-PKA-Hippo pathway, which is supported by a recent review." (PMID 34510318, 2022). "In comparison between different breast cancer cell lines, the triple-negative cell lines MDA-MB-468 and MDA-MB-231 showed a lower relative LPAR6 RNA expression, whereas LPAR6 RNA expression was higher in luminal A breast cancer cell lines." (PMID 39338222, 2024).
breast carcinoma (continued). "Although LPA receptor 6 (LPAR6), the last identified LPA receptor, has been reported to have diverse effects in multiple cancers, including breast cancer, its effects and functioning mechanisms are not fully known." (PMID 34510318, 2022). "Correlation analyses also supported that LPAR6 and RB1 shared similar expression patterns both in healthy breast tissues and breast cancer tissues." (PMID 34510318, 2022). "Our study validates the tumor suppressor role of LPAR6 through in vitro experiments of representative cell lines of luminal and HER2 subtypes of breast cancer." (PMID 34510318, 2022). "Overall, the LPAR6 expression level is significantly correlated with prognosis in all patients with breast cancer, even in HR + patients, regardless of LN metastatic status." (PMID 34510318, 2022). "Proliferation and/or motility of cancer cells were promoted after LPA signalling through the LPAR1 in colon, gastric, and breast cancer, LPAR2 in colon and renal cancer, LPAR3 in colon, pancreatic, and breast cancer, LPAR4 in fibrosarcoma, and LPAR6 in hepatic and pancreatic cancer." (PMID 34722305, 2021). "Additionally, high LPAR6 expression significantly impacts disease-specific survival (DSS) in bladder cancer and OS, relapse-free survival (RFS), DSS, distant metastasis-free survival (DMFS) in breast cancer." (PMID 34769557, 2021). "Interestingly, we found that the expression level of LPAR6 expression correlates with better OS and high immune-infiltration levels in breast cancer, liver cancer and LUAD rather than in LUSC." (PMID 34769557, 2021).
melanoma (7 papers, 2019 to 2023). A malignant, usually aggressive tumor composed of atypical, neoplastic melanocytes. "Reversely, proliferation and/or motility of cancer cells also showed a decrease after LPA signalling through LPAR2 in melanoma, LPAR4 in pancreatic, colon, and head and neck cancer, LPAR5 in pancreatic cancer and melanoma, and LPAR6 in colon cancer." (PMID 34722305, 2021). "Specifically, TILs derived from three melanoma patients predominantly expressed LPAR6 with low expression of LPAR2, whereas peripheral CD8+ T cells expressed LPAR6 > LPAR2 > LPAR5 > LPAR4." (PMID 32397679, 2020). "In addition, another group discovered that LPAR6 can negatively regulate T cell migration and found a significant inverse correlation between RNA levels of ATX and CD8+ T cell infiltration in melanoma patients." (PMID 37655662, 2023).
liver cancer (6 papers, 2016 to 2025). An epithelial or non-epithelial malignant neoplasm that arises from the liver. "A better prognosis in liver cancer is shown to be associated with a higher LPAR6 expression level." (PMID 34769557, 2021). "To confirm the consistency between the in vitro results and the in vivo role of LPAR6, we established a human liver cancer cell xenograft model in nude mice, extending the study to an animal experiment level." (PMID 40362442, 2025). "Therefore, increasing the diversity of cell lines and considering the factors of the tumor microenvironment will contribute to a more comprehensive understanding of the role of LPAR6 in liver cancer." (PMID 40362442, 2025).
prostate carcinoma (5 papers, 2017 to 2025). A carcinoma that arises from epithelial cells of the prostate gland. "Nevertheless, we found similar prognostic associations between LPAR6 expression in bladder, breast, cervical, colorectal, esophageal, lung and prostate cancers in these databases." (PMID 34769557, 2021). "Enhanced LPAR6 signalling promotes migration of prostate cancer cells and its overexpression is associated with squamous cell carcinomas of the lung, cervix, skin, urinary bladder, testis, head and neck." (PMID 29211777, 2017). "Higher level of LPAR6 correlates with increased migration, invasion and tumour reoccurrence in the androgen independent prostate cancer cells." (PMID 29211777, 2017). "Thus BuIA may serve as a natural peptide-based antagonist to competitively inhibit the LPA binding site of LPAR6 in prostate cancer and squamous cell carcinoma." (PMID 29211777, 2017).
hypotrichosis simplex (4 papers, 2021 to 2023). Hypotrichosis simplex (HS) or hereditary hypotrichosis simplex (HHS) is characterized by reduced pilosity over the scalp and body (with sparse, thin, and short hair) in the absence of other anomalies. "Several genes have been identified as being associated with hypotrichosis simplex, including LPAR6, LIPH, and DSG4." (PMID 36685177, 2022). "More than that, LPAR6 is highly expressed in hair follicles, especially IRS, thus indicating the crucial role it plays in hair follicle development and hair growth and its association with Hypotrichosis 8 and Familial Woolly Hair Syndrome." (PMID 37443815, 2023).
alopecia (3 papers, 2016 to 2025). Hair loss usually from the scalp. "Biallelic loss-of-function variants in LPAR6 cause hypotrichosis type 8 (OMIM 278150), with or without woolly hair, a form of non-syndromic alopecia." (PMID 27472364, 2016).
autosomal recessive hypotrichosis (3 papers, 2021 to 2025). "Additionally, mutations in LPAR6, LIPH, and DSG4 genes have been identified in patients with autosomal recessive hypotrichosis with similar presentations." (PMID 39845463, 2025).
hair disorder (3 papers, 2013 to 2025). "Several causative genes containing mutations for hereditary hair diseases have been identified in the recent years, but this is the first characterized mutation within LPAR6 associated with a curly phenotype in an animal other than humans." (PMID 23826204, 2013).